TIGD3 (tigger transposable element derived 3)
Tractability: No criterion of Open Targets' tractability assessment is met for any kind of drug.
Gene: Protein-coding gene on chromosome 11 (65,354,751 to 65,357,613, forward strand). Ensembl gene ENSG00000173825.
Subcellular location: Nucleus
Subcellular location (Human Protein Atlas): Nuclear membrane; Nucleoplasm
Gene Ontology:
Molecular function: protein binding; DNA binding; nucleic acid binding
Cellular component: nucleus
Genetic constraint (gnomAD): Loss-of-function variants: 15 observed, 18.94 expected, observed/expected ratio (o/e) 0.79, 90% interval 0.53 to 1.22. The upper end of that interval is the gene's LOEUF score, 1.22, which puts it in group 5 of 6, group 1 being the genes least tolerant of losing a copy. Missense variants: 581 observed, 628.01 expected, observed/expected ratio (o/e) 0.93, 90% interval 0.86 to 0.99. Synonymous variants: 243 observed, 278.56 expected, observed/expected ratio (o/e) 0.87, 90% interval 0.79 to 0.97.
Homologues: Orthologues: chimpanzee TIGD3 (99% identical), dog TIGD3 (88% identical), pig TIGD3 (87% identical), guinea pig TIGD3 (85% identical), mouse Tigd3 (83% identical), rat Tigd3 (83% identical). Paralogues in human: CENPB (26% identical), TIGD4 (26% identical), TIGD6 (22% identical), TIGD5 (22% identical), JRK (20% identical), JRKL (20% identical), TIGD1 (18% identical), TIGD7 (18% identical), TIGD2 (17% identical), POGK (14% identical), POGZ (13% identical).
Diseases named in the same sentence as TIGD3 in open-access papers:
TIGD3 is named in the same sentence as 1 disease in open-access papers, as found by Europe PMC text mining. Sharing a sentence is not in itself a finding about the gene and the disease. The quoted sentences say what the papers report.
cancer (1 paper, 2022). A tumor composed of atypical neoplastic, often pleomorphic cells that invade other tissues. "Nonetheless, there is little information regarding the biological functions of PPP1R27 and TIGD3 in cancer." (PMID 35676660, 2022).